RN7SL233P (RNA, 7SL, cytoplasmic 233, pseudogene)
Gene: Miscellaneous RNA gene on chromosome 18 (21,793,883 to 21,794,159, forward strand). Ensembl gene ENSG00000242971.
Homologues: Orthologues: chimpanzee Metazoa_SRP (91% identical), dog Metazoa_SRP (48% identical). Paralogues in human: RN7SL3 (82% identical), RN7SL1 (81% identical), RN7SL2 (80% identical), RN7SL220P (80% identical), RN7SL45P (79% identical), RN7SL559P (78% identical), RN7SL218P (78% identical), RN7SL769P (78% identical), RN7SL586P (77% identical), RN7SL630P (77% identical), RN7SL778P (77% identical), RN7SL145P (77% identical), and 701 more.